LINC01001 (long independently transcribed non-coding RNA 1001)
Gene: Long non-coding RNA gene on chromosome 11 (126,990 to 139,612, reverse strand). Ensembl gene ENSG00000230724.
Diseases named in the same sentence as LINC01001 in open-access papers:
LINC01001 is named in the same sentence as 3 diseases in open-access papers, as found by Europe PMC text mining. Sharing a sentence is not in itself a finding about the gene and the disease. The quoted sentences say what the papers report.
ischemic stroke (1 paper, 2021). A stroke disorder caused by obstruction of blood flow to the brain, due to thrombotic (local blood clot formation) or embolic (due to a blood clot or other material traveling from another site) event. "lncRNA-miRNA-mRNA regulatory axis such as SND1-IT1/NAPA-AS1/LINC01001-miR-24-3p-LPAR3/ADORA1 and LUCAT1/ASAP1-IT2-miR-93-3p-GPR17 may play important roles in the progression of ischemic stroke." (PMID 34483854, 2021). "Regulatory axis, such as SND1-IT1/NAPA-AS1/LINC01001-miR-24-3p-LPAR3/ADORA1 and LUCAT1/ASAP1-IT2-miR-93-3p-GPR17 may play important roles in the progression of ischemic stroke." (PMID 34483854, 2021). "Thus, we speculated that KCNQ1OT1, SND1-IT1, NAPA-AS1, and LINC01001 may interact with miR-24-3p and facilitate the regulation of LPAR3 and ADORA1 in ischemic stroke." (PMID 34483854, 2021).
lung adenocarcinoma (1 paper, 2021). A carcinoma that arises from the lung and is characterized by the presence of malignant glandular epithelial cells. "It has been reported that LINC01001 is highly expressed in lung adenocarcinoma and is related to the poor prognosis of patients." (PMID 34630126, 2021). "Researches have shown that LINC01001 is highly expressed in lung adenocarcinoma and is related to the poor prognosis of patients." (PMID 34630126, 2021).
tumor (1 paper, 2021). "Further studies were performed to investigate the roles of LINC01001 in crizotinib-resistant NSCLC tumor growth." (PMID 34630126, 2021). "Furthermore, to investigate whether LINC01001 regulates crizotinib-resistant NSCLC tumor growth via MYC, pcDNA-LINC01001 and sh-MYC plasmids were co-transfected into H1299/R cells to overexpress LINC01001 and knockdown MYC, respectively." (PMID 34630126, 2021). "Subsequently, H1299/R cells where LINC01001 was overexpressed and MYC was inhibited were subcutaneously injected into BALB/C nude mice for tumor information (n = 7)." (PMID 34630126, 2021). "Our results furtherly indicated that LINC01001 overexpression accelerates crizotinib-resistant NSCLC cell proliferation, inhibits apoptosis, and accelerates tumor growth via IGF2BP2/MYC axis, indicating LINC01001 regulates crizotinib-resistance NSCLC progression by modulating IGF2BP2/MYC axis." (PMID 34630126, 2021).